ALB (albumin)
Diseases named in the same sentence as ALB in open-access papers (continued):
Sharing a sentence is not in itself a finding about the gene and the disease.
infection (continued). "Hospitalization in the last 6 months, intra-abdominal source of infection, presence of organ failure, and altered levels of blood biomarkers, including C-reactive protein, albumin, and lactate were significant risk factors for 90-day mortality." (PMID 33267829, 2020). "In light of how accurately the decrease in albumin level would predict an adverse outcome, delta albumin was associated with surgical site infection." (PMID 32664910, 2020). "In the present study, we first showed that higher albumin-corrected serum calcium level was significantly associated with increased risk of infection-related death in patients receiving hemodialysis." (PMID 32286455, 2020). "Nevertheless, in this study, lower BMI was revealed to be independent risk factor for all-cause mortality and infection-related death, even after adjusting for confounding factors including elderly age, and serum albumin level." (PMID 32605606, 2020). "Many previous studies have identified risk factors for infection-related mortality in patients undergoing PD, including age, diabetes mellitus, serum potassium, serum albumin, serum creatinine, serum phosphate, and other variables." (PMID 30893369, 2019). "Patients with low serum or ascitic fluid albumin have also been shown to be at increased risk of infection but the immunoregulatory effects of albumin administration are still unclear." (PMID 30873165, 2019). "With other serologic markers including CRP, prothrombin time, aPTT, creatinine, and albumin associated with infection, DNI significantly predicted death within 30 days after abdominal surgery." (PMID 30985959, 2019). "This study also showed that lower serum albumin level was a significant risk factor for severe infection in AAV patients, as previously reported." (PMID 31349802, 2019). "Univariate CPH analyses identified several statistically significant predictors of increased infection risk, namely, lower serum albumin level, higher serum creatinine level, use of methylprednisolone pulse, and OC." (PMID 31349802, 2019). "In patients receiving HD, serum albumin and hsCRP were independent predictors of all-cause, cardiovascular, and infection-related mortalities (all P < 0.05)." (PMID 29494637, 2018). "The CONUT score is composed of serum albumin, cholesterol level and the lymphocyte count, which were associated with immune response, infection, inflammation, tissue repair and regeneration." (PMID 30194336, 2018). "In the subgroup analysis, low phosphate in patients aged 65 years or older or on dialysis more than one year or with a serum albumin level less than 3.9 mg/dL was significantly associated with infection-related mortality." (PMID 28973026, 2017). "Surigical site infection has been a challenge for surgeons for many years, the prevalence of serum albumin <3.5g/dL has been reported to be associated with increased orthopaedic complications." (PMID 28093079, 2017). "Risk factors for infection in the population exposed to systemic glucocorticoids with data on albumin level and lymphocyte count (n = 34,401)." (PMID 27218256, 2016). "Event numbers were too little to carry out multivariate analysis for severe infection or marked albumin loss." (PMID 26161663, 2015). "Significant preoperative factors associated with delayed healing included infection with methicillin-resistant Staphylococcus aureus, vascular disease, albumin level ≤3.0 g/dL, and greater extent of tissue loss." (PMID 25692151, 2015). "In the context of any infection, the use of albumin was associated with reduced risk of death OR 0.46 95% CI 0.25–0.86, I2 = 24% and renal impairment OR 0.34 95% CI 0.15–0.75, I2 = 34%." (PMID 24222902, 2013). "Infection also caused significant increases in the levels of globulin and decreases in the levels of albumin, alkaline phosphatase, triglyceride and the albumin-to-globulin ratio." (PMID 20824219, 2010).
infection (continued). "Second, reliance on a single admission measurement of the MAR prevents the assessment of temporal dynamics and trajectory-based risk; unmeasured influences on monocytes and albumin, such as intercurrent infection, hydration status, and hepatic function, cannot be fully excluded." (PMID 41479615, 2025). "Routine albumin surveillance may help identify high-risk patients and prompt targeted interventions - nutritional optimization, infection/inflammation management, and dialysis adequacy checks - to reduce healthcare utilization and improve clinical outcomes." (PMID 41552166, 2025). "Previous studies have identified severe edema, ascites blood albumin below 15 g/L, blood cholesterol higher than 400 mg/dL, and the use of a combination of glucocorticoids and immunosuppressants as factors associated with infection in patients with INS." (PMID 41291834, 2025). "Similarly, PNI, calculated from serum albumin and lymphocyte counts, integrates nutritional depletion and immune incompetence—two interdependent factors exacerbating catabolic states and infection susceptibility in ICU settings." (PMID 40771209, 2025). "Serum albumin levels have also been widely associated with infection risk." (PMID 39773012, 2025). "Furthermore, each component of the HALP score—hemoglobin, albumin, lymphocyte count, and platelet count—is susceptible to fluctuations due to extrinsic factors such as hydration status, infection, nutritional deficiencies, or comorbid hematologic conditions." (PMID 41227180, 2025). "The small to moderate effect size further suggests that while albumin may serve as a potential marker for infection risk, its predictive value might be limited in isolation." (PMID 40566087, 2025). "In addition to this, the decrease in serum ALB levels has a direct impact on the functioning of innate immunity and antimicrobial defenses, thereby increasing the susceptibility to infection complications." (PMID 41244105, 2025). "The results highlight the multifactorial etiology of SSIs and the need for optimized perioperative strategies, including reduced operative duration, prudent transfusion and albumin use, and targeted antimicrobial prophylaxis, to minimize postoperative infection risk." (PMID 41471171, 2025). "For example, an inverse correlation between lactate and albumin might be expected in high-inflammatory states with capillary leakage, whereas in more localized infections such as urinary sepsis, this association could be weaker or absent." (PMID 41590227, 2025). "Higher age, WBC, wasit and lower ALB were linked to a higher infection probability." (PMID 40584706, 2025). "A hierarchical regression analysis was conducted to examine whether the GNRI provides additional predictive value for postoperative infection risk, beyond established nutritional biomarkers (albumin, prealbumin) and age." (PMID 40507204, 2025). "Poor nutritional status, as evidenced by reduced albumin, can lead to muscle weakness, decreased immune function, and an increased risk of infection, all of which may precipitate POD." (PMID 40168626, 2025). "Infection by SAR-CoV-2 worsened the ADL functional capacities as measured by BI and also reduced albumin levels, which could be a potential biomarker related to hepatic physiological changes associated with their infection/inflammatory processes." (PMID 39846571, 2024). "Therefore, serum albumin level, residence, and hematuria were the factors significantly associated with infection." (PMID 38987746, 2024). "Another major change during infection and inflammation is a decrease in the amount of albumin in the serum, which may reflect selective loss of albumin due to renal or gastrointestinal changes or a decrease in hepatic synthesis." (PMID 38540062, 2024).
infection (continued). "Except in type C ACLF, a gradual decline in both platelet count and albumin levels, along with a slow increase in lactate after treatment, predict poor outcomes and increased risk of hypotension, bleeding, shock, infection, and hepatic encephalopathy during future artificial liver therapy." (PMID 38245594, 2024). "Our study also demonstrated that albumin could serve as a biomarker to predict the risk of infection in renal transplant recipients." (PMID 39583098, 2024). "Furthermore, reducing albumin levels amplifies the susceptibility to infection in patients with CRE colonization." (PMID 38680915, 2024). "Analysis of the sensitivity of preoperative low albumin levels on the risk of postoperative incision infections indicated a significant increase in risk, with high consistency across the study results reflected by the combined effect size (OR = 0.12, 95% CI: 0.02–0.76)." (PMID 39193402, 2024). "Low albumin levels have been associated with an increased risk of infection." (PMID 39583098, 2024). "Another study including free and pedicled myocutaneous flaps for oral cavity reconstruction further identified postoperative infection and decreased serum albumin levels as factors that were significantly associated with reduced flap volume 6 and 12 months after insertion." (PMID 39200956, 2024). "Given the important role of albumin in reflecting the body’s nutritional status, decreased levels may lead to impaired immune function and increase the risk of infection." (PMID 38481940, 2024). "In multivariable logistic regression analysis, immunosuppressants [odds ratio (OR), 19.132; 95% confidence interval (CI), 1.349–271.420; P = 0.029] and serum albumin levels (OR, 0.817; 95% CI, 0.668–0.999; P = 0.049) were independent risk factors for developing infections." (PMID 38680915, 2024). "In addition, low ALB levels lead to a decrease in patients' immunity and resistance, which can easily cause complications such as infection, prolonging the course of the disease, and resulting in poor prognosis for GBS patients." (PMID 38099064, 2023). "However, in patients suffering from severe infections, albumin is markedly reduced, which is associated with adverse clinical outcomes." (PMID 37790597, 2023). "Our data support that YTY-containing ACE2, in the context of a dimeric fusion with the QMP albumin variant, demonstrates improved viral binding and blockage of cellular infection against Delta (B.1.617.2) and Omicron (B.1.1.529, BA.5, BQ.1.1, and XBB) variants, in comparison with WT ACE2." (PMID 38077689, 2023). "Ongoing inflammation derived from severe infection may cause a reduction in synthesis and an increase in catabolism of albumin." (PMID 36830256, 2023). "On the other hand, inflammatory factors such as IL-6 and TNF-α could affect the synthesis of albumin by hepatocytes, thus increasing the risk of infection and promoting the invasion and metastasis of tumors." (PMID 37495731, 2023). "In addition, during the infection-caused OS, an excessive amount of dysfunctional albumin is generated and degraded rapidly." (PMID 37629114, 2023). "Albumin had a stronger predictive ability in apparently less severe patients, suggesting a role as a rapid marker of the early microvascular changes associated with infection mortality." (PMID 37240554, 2023). "Infection with S. mansoni was associated with substantial changes in the histological architecture of liver tissue and abnormal levels of hepatic function tests (albumin, AST, and ALT)." (PMID 37964174, 2023). "A lower albumin value is related to a higher risk of surgical site infections." (PMID 37611242, 2023). "Symptomatic breakthrough infection in this group was also associated with lower serum albumin." (PMID 37870985, 2023). "Therefore, the association between preoperative low albumin levels and acute postoperative infection is likely to be complex." (PMID 36684164, 2022).
infection (continued). "Albumin and globulin, easily accessible and reliable biomarkers in the basic metabolic panel, have proven to be critical markers associated with inflammation and infection." (PMID 36309703, 2022). "Poor nutritional status may lead to a heavy volume load and chronic inflammation by reducing plasma albumin levels, thereby resulting in higher all-cause mortality, cardiovascular events and infection-related mortality." (PMID 36545333, 2022). "In addition to the serum albumin level being a reliable predictor to assess postoperative complications, it is also a risk factor for postoperative infection in orthopedic surgery." (PMID 36684164, 2022). "We argue that pathological mechanisms of elevated NAR related both to an excessive neuroinflammation response, indicated by increased neutrophil, and albumin decrease that might result in susceptibility to infection as POP." (PMID 35463142, 2022). "It has already been demonstrated that a low concentration of serum albumin is strongly associated with reduced kidney function, which may also cause infection in kidney recipients." (PMID 36117592, 2022). "Our final proposition is that therapeutic albumin should be: (i) chosen as 4% albumin with a high potential of antioxidant activity; (ii) infused continuously at a rate of 10–12 mL/kg/24 h over 5 days to limit the risk of care-related infections." (PMID 36297613, 2022). "In addition, the statistical trend was consistent with our previous results that albumin levels were associated with acute postoperative infection (OR 0.897; 95% CI 0.822–0.980; P = 0.015)." (PMID 36684164, 2022). "Low serum albumin may indicate poor nutritional conditions with the inability to secrete albumin in the liver or severe infections with an increase in immunoglobulin-suppressing albumin production, which can cause high mortality." (PMID 35602847, 2022). "Thus, albumin infusion is needed for those with a low level of serum albumin during the follow-up period, which has been recognized as an independent risk factor for infection." (PMID 36117592, 2022). "Associations with infectious diseases might also lead to the identification of low albumin levels as a culprit, causally contributing to both the acquisition and development of complications of infections." (PMID 36292245, 2022). "Only low albumin was most strongly associated with infection risk and adverse outcome." (PMID 35119125, 2022). "The fact that C. glabrata highly up-regulated the gene encoding for Aus1 during infection once albumin is present may indicate that cholesterol efflux also may occur in our model." (PMID 34710198, 2021). "Accordingly, a seven-fold increased risk of arthroplasty-related infections was observed at a preoperative albumin level of <35 g/L; however, proteins are essential for adequate wound healing and serve as carriers for most vitamins (such as vitamin D and its metabolites), hormones, and mediators." (PMID 32424439, 2021). "As the genes involved in response to oxidative stress were significantly up-regulated, we checked whether ROS production by epithelial cells was increased during infection in the presence of albumin and therefore causing an additional stress for the fungus." (PMID 34710198, 2021). "In a rabbit PJI model, grit-blasted pure titanium implants were coated with cross-linked albumin and compared against an uncoated control and were exposed to S. epidermidis before implantation; the cross-linked albumin implants experienced a lower infection rate than the uncoated implants." (PMID 34638591, 2021). "A previous study disclosed that mortality caused by infection in individuals with both a decreased estimated glomerular filtration rate and an elevated albumin to creatinine ratio was approximately 100- to 300-fold higher for chronic dialysis patients than for the general public." (PMID 33466271, 2021).
infection (continued). "The consistent association between inflammation and albumin makes the hypothesis of an inflammatory result as responsible for albumin reduction translating into a more severe infection." (PMID 34768653, 2021). "Additionally, it is well-known that high neutrophil percentage predicts bloodstream infection, while low albumin levels increase the susceptibility to infection complications." (PMID 34566849, 2021). "In addition, stress caused by severe infection accelerates the catabolism of serum albumin, significantly shortening its half-life." (PMID 34722573, 2021). "Moreover, the albumin and cholinesterase levels were even lower in those cases with the risk of secondary infection, highlighting a link between liver injury at the initial infection stage and the secondary infections." (PMID 34659204, 2021). "It is reasonable to assume that albumin treatment might ameliorate the number of deaths caused by infection or infection-related organ failures." (PMID 32576140, 2020). "Furthermore, the plasma protein loss from the primary infection will result in the synthesis of lipoproteins and low albumin levels." (PMID 33299427, 2020). "Another potential explanation for the association between serum albumin-corrected calcium level and infection-related death may be calcium-induced increases in circulating FGF23 and calciprotein particles (CPPs)." (PMID 32286455, 2020). "Besides, lower serum albumin levels, along with older age and higher nHF, were independent predictors for infection-associated mortality." (PMID 31964940, 2020). "We determined the effect modifications in subgroups stratified by baseline characteristics for the association between every 1 mg/dL increase in albumin-corrected serum calcium level and incidence of infection-related death by multivariable Cox proportional hazard risk analysis." (PMID 32286455, 2020). "This may reflect the physician’s lack of confidence in the results of a dipstick test since urinary albumin excretion can also be affected by other factors and conditions such as exercising in the 24 h prior to testing, infection, and fever." (PMID 33106200, 2020). "Generally, albumin is thought to be safer than artificial colloids because it is derived from human albumin, but it can also be more expensive, has ethical implication as a human blood product, and is associated with a higher risk of infection." (PMID 32783070, 2020). "A Fine–Gray subdistribution hazards model showed that higher albumin-corrected serum calcium level was significantly associated with heightened risk of infection-related death (HR [95% CI] per every 1 mg/dL increase in albumin-corrected serum calcium level: 1.52 [1.21–1.90], P < 0.001)." (PMID 32286455, 2020). "Low level of blood albumin could promote and aggravate circulatory congestion and strengthen oxidative stress, inflammatory response, and susceptibility to infection, which could worsen the prognosis of patients with CHF." (PMID 33282007, 2020). "Although dipstick urinalysis might be less accurate than the urine albumin-to-creatinine ratio, the present findings demonstrated its usefulness in predicting risks of infection-associated hospitalization and mortality in older CKD patients." (PMID 32161271, 2020). "Both, BMI and serum albumin are linearly associated with reduced risk of infection-related death." (PMID 30651062, 2019). "Old age and lower albumin level were the risk factors for infection events." (PMID 31167651, 2019). "Furthermore, we found that the change of ALB level was an independent risk factor for postoperative infection in patients underwent McKeown esophagogastrectomy." (PMID 31772939, 2019). "Age, albumin level, and category of infection have been shown to associate with poor outcomes." (PMID 31167651, 2019). "Additional analyses were conducted to determine whether the PCT/albumin ratio was associated with the severity of infection in patients with urosepsis." (PMID 29995751, 2018).